BUB3 (BUB3 mitotic checkpoint protein)
Diseases named in the same sentence as BUB3 in open-access papers (continued):
Sharing a sentence is not in itself a finding about the gene and the disease.
melanoma (3 papers, 2014 to 2024). A malignant, usually aggressive tumor composed of atypical, neoplastic melanocytes. "There was also upregulation of Matrin-3, a downstream component of the FGF2 pathway that mediates melanoma cell proliferation and survival, and BUB3, a mitotic checkpoint regulator." (PMID 39272836, 2024). "Taken together, our study has identified novel insights into SIRT1 signaling in melanoma by connecting this important protein deacetylase with spindle assembly check point proteins BUB3, BUB1 and BUBR1." (PMID 24743044, 2014). "However, PSAP, MYO1B and BUB3 seem to follow the same trend as shown by proteomics analysis in all three melanoma cell lines." (PMID 24743044, 2014). "Tenovin-1 treatment was found to result in a significant decrease in BUB3, BUB1 and BUBR1 proteins in melanoma cells." (PMID 24743044, 2014). "The qRT-PCR and immunoblot analyses showed that tenovin-1 inhibition of SIRT1 resulted in a downregulation of BUB3, BUB1 and BUBR1 in multiple melanoma cell lines." (PMID 24743044, 2014). "Therefore, as the next step, we analyzed the effect of tenovin-1 on protein levels of BUB3, BUB1 and BUBR1 in all three melanoma cell lines." (PMID 24743044, 2014).
osteosarcoma (3 papers, 2021 to 2024). A usually aggressive malignant bone-forming mesenchymal neoplasm, predominantly affecting adolescents and young adults. "Mutations or deletions in Bub3 have been found in CRC, osteosarcoma and other tumors." (PMID 34882895, 2022).
glioma (2 papers, 2011 to 2022). A benign or malignant brain and spinal cord tumor that arises from glial cells (astrocytes, oligodendrocytes, ependymal cells). "The expression of Bub3 mRNA was downregulated and associated with tumor grade and prognosis in glioma tumors." (PMID 34882895, 2022). "RNA levels of eight major mitotic spindle assembly checkpoint (SAC) genes (BUB1, BUB1B, BUB3, CENPE, MAD1L1, MAD2L1, CDC20, TTK) significantly correlated with glioma grade and six also significantly correlated with survival time." (PMID 22022424, 2011). "Nevertheless, antibody stains for proteinsBUB1, BUB1B, BUB3, CDC20, and TTK were at significantly higher levels in high grade glioma than in normal brain by this test." (PMID 22022424, 2011).
lymph node metastasis (2 papers, 2022 to 2023). "BUB3 expression level was correlated with the status of lymph node metastasis." (PMID 36787437, 2023). "Additionally they reported that the expression of Bub3 mRNA was associated with tumor, node, metastases (TNM) staging, clinical staging and lymph node metastasis." (PMID 34882895, 2022). "Bub3 mRNA expression was elevated if OSCC tissue was in T3–T4/with lymph node metastasis." (PMID 34882895, 2022).
non-small cell lung carcinoma (2 papers, 2013 to 2023). A group of at least three distinct histological types of lung cancer, including non-small cell squamous cell carcinoma, adenocarcinoma, and large cell carcinoma. "The expression level of Bub3 is highly related to the incidence of non-small cell lung cancer." (PMID 36787437, 2023).
ovarian carcinoma (2 papers, 2024 to 2025). A malignant neoplasm originating from the surface ovarian epithelium. "The findings showed that high expression levels of BUB1B, BUB3, or TTK were associated with better survival rates in ovarian cancer patients treated with paclitaxel compared to patients with low expression levels." (PMID 38410481, 2024). "A Kaplan-Meier survival analysis was carried out to determine the relationship between the expression of BUB1B, TTK, and BUB3 and the overall survival and recurrence-free survival of ovarian cancer patients treated with paclitaxel." (PMID 38410481, 2024). "Silencing of either Bub3 or BuGZ has previously shown to enhance exon skipping in Human foreskin fibroblast (i.e. HFF) and ovarian carcinoma TOV21G cell lines." (PMID 40025502, 2025).
polyposis (2 papers, 2018 to 2022). "We performed a mutational analysis of BUB1 and BUB3 in 456 uncharacterized mismatch repair-proficient hereditary non-polyposis CRC families and 88 polyposis cases." (PMID 29448935, 2018).
abortion (1 paper, 2021). the ending of pregnancy by removing a fetus or embryo before it can survive outside the uterus. "Among them, MAD2 and BUBR1 overexpression can facilitate correct chromosome segregation and embryo stability, though the expression levels of MAD1 and BUB3 in aneuploid abortion remain unknown." (PMID 33902659, 2021). "However, miR-125b, Mad1 and Bub3 gene expression in aneuploid embryos of spontaneous abortion has not been reported to date." (PMID 33902659, 2021).
aneuploidy (1 paper, 2021). Chromosomal disorder consisting of the presence a chromosomal abnormality in which there is an addition or loss of chromosomes within a set. "statistical analysis (p < 0.05) showed that miR-125b and BUB3 were significantly down-regulated in the aneuploidy group compared to the control group and that MAD1 was significantly up-regulated." (PMID 33902659, 2021).
colon adenocarcinoma (1 paper, 2022). "Furthermore, the TCGA database was used in this study to examine the expression level of BUB3 in colon adenocarcinoma (COAD)." (PMID 35156516, 2022).
Dengue virus infection (1 paper, 2025). "Key regulatory genes such as AURKA, BUB1, BUB3, and CDK1 are found to be involved in cell cycle regulation and have roles in immune-related pathways, underscoring their importance in the host immune response to Dengue virus infection." (PMID 40100920, 2025).
depression (1 paper, 2022). "However, the association between BUB3 SNP and the pathophysiology of migraine or depression remains unclear and warrants further analysis." (PMID 36704746, 2022).
developmental delay (1 paper, 2017). "Consistent with the role of precocious M-phase entry playing a part in conferring IR sensitivity, we found that treatment of both bub-3 and fzy-1(av15) mutants led to a heightened sensitivity to IR, based on developmental delay phenotypes and the increased incidence of the ruptured vulva phenotype." (PMID 29046436, 2017).
fibrosarcoma (1 paper, 2021). A malignant mesenchymal fibroblastic neoplasm affecting the soft tissue and bone. "BUB3 was upregulated in synovial sarcoma, fibrosarcoma, and malignant fibrous histiocytoma." (PMID 33872216, 2021).
Infertility (1 paper, 2023). "TUBB8 and BUB3 were already associated with infertility due to oocyte meiotic arrest and mosaic variegated aneuploidy syndrome, respectively." (PMID 36999055, 2023).
lactic acidosis (1 paper, 2013). Metabolic acidosis characterized by the accumulation of lactate in the body. "Since hyperactivated mitotic checkpoint is another major mechanism that leads to human tumor CIN, we tested if glucose deprivation with lactic acidosis could disturb the expression of the mitotic checkpoint genes such as mad2, bub1, bub3, and bub1b." (PMID 23675453, 2013).
leukoplakia (1 paper, 2021). A white patch or plaque on a mucous membrane that cannot be characterized clinically or pathologically as any other disease. "We analysed the immunoexpression of BubR1, Mad2, Bub3, and Spindly proteins in 64 oral biopsies from 52 oral leukoplakias and 12 normal tissues." (PMID 34704983, 2021).
liver cancer (1 paper, 2023). An epithelial or non-epithelial malignant neoplasm that arises from the liver. "The expression level of BUB3 was significantly elevated in cases of cervical, bladder, head, brain, colorectal, central nervous system, gastric, head, blood, and liver cancer." (PMID 36787437, 2023).
lung adenocarcinoma (1 paper, 2023). A carcinoma that arises from the lung and is characterized by the presence of malignant glandular epithelial cells. "In the current study, we reveal a positive association between the BUB3 gene and human LUAD and the lung adenocarcinoma cell lines." (PMID 36787437, 2023).
lymphoma (1 paper, 2025). A malignant (clonal) proliferation of B- lymphocytes or T- lymphocytes which involves the lymph nodes, bone marrow and/or extranodal sites. "Similarly, the suppression of BUB3, CCNB1, CDCA8, and CDK1 supported mitotic disruption and proliferative collapse in the HKB-11 lymphoma cells upon treatment with the N and UB combination." (PMID 40725093, 2025).
myxofibrosarcoma (1 paper, 2021). A malignant fibroblastic neoplasm arising from the soft tissue. "BUB3 was upregulated in myxofibrosarcoma with a 2.514 (P = 1.57E-12) fold change." (PMID 33872216, 2021).
serous ovarian cancer (1 paper, 2024). "The findings showed that high expression levels of BUB1B, BUB3, or TTK were associated with better survival rates in serous ovarian cancer patients treated with paclitaxel compared to patients with low expression levels." (PMID 38987356, 2024).
viral infection (1 paper, 2022). "In conclusion, the host Bub3 was found to interact with ARV p17 upon viral infection, which was important for arresting the host cell cycle in the G2/M phase." (PMID 36366482, 2022). "Considering that some cell-cycle regulators can influence both cell division and programmed cell death according to different cellular environments and genetic backgrounds, Bub3 might also play an important but not a sole role in the different stages of viral infection." (PMID 36366482, 2022).
cancer (36 papers, 2002 to 2024). A tumor composed of atypical neoplastic, often pleomorphic cells that invade other tissues. "Overall, these studies confirm that the overexpression of the BUB3 gene and protein is a common feature of human cancers, being associated with poor prognosis." (PMID 35631670, 2022). "Upregulation of the BUB3 gene has been found in a variety of human cancers and is associated with poor prognoses." (PMID 35631670, 2022). "BUB3 up-regulation was found in multiple human cancers, including NSCLC, and was linked to poor prognoses." (PMID 36551208, 2022). "Here, we review the structure and functions of BUB3 in mitosis, its expression in cancer and association with survival prognoses, and its potential as an anticancer target." (PMID 35631670, 2022). "The loss of Bub3 function results in chromosomal dysregulation and aneuploidy, contributing to cancer evolution." (PMID 34882895, 2022). "A high expression of BUB3 was an independent prognostic indicator for cancer-specific survival and was associated with increased cellular proliferation." (PMID 32596342, 2020). "CCNB1 and cytoplasmic BUB3 scores were integrated with the Cancer of the Prostate Risk assessment post-Surgical (CAPRA-S) score by adding two points for each marker if they were positive." (PMID 31801961, 2020). "Inhibition of BuGZ results in loss of both Bub3 and its binding partner Bub1 from kinetochores, and lethal chromosome congression defects in cancer cells." (PMID 28553202, 2017). "BUB3 is frequently implicated in cancer for causing genome instability." (PMID 36949074, 2023). "Importantly, the BUB3 gene is upregulated in most cancers studied, which is generally associated with poor outcomes." (PMID 35631670, 2022). "Inhibiting the activity of BUB1B, TTK, and BUB3 can impede cancer cell proliferation, migration, and invasion." (PMID 38410481, 2024). "BUB3 regulated mitosis of eukaryotic cells and has been closely related to tumorigenesis of a variety of cancers." (PMID 37301543, 2023). "Here, we reviewed BUB3′s functions in cell cycle progression, its roles in human cancers, and its potential as a target for cancer treatment." (PMID 35631670, 2022). "Strategies to mimic Bub3/Rae1 haploinsufficiency in order to induce premature senescence of cancer cells should be explored." (PMID 35631670, 2022). "The expression level of BUB3 continuously maintained a high expression status from stage 1 to stage 4 of cancer stages, and the highest expression level was detected in stage 1." (PMID 35156516, 2022). "Previous studies have reported BUB3 overexpression, at both RNA and protein levels, in a variety of human cancers compared with normal tissue." (PMID 35631670, 2022). "BUB3 transcript levels were compared between cancers and normal tissue in 18 cancer types; 17 cancer types were excluded from the analysis due to lack of normal samples." (PMID 35631670, 2022). "In this review, we summarize the expression and clinical significance of Bub3 in a variety of tumors and suggest that it has potential in the treatment of cancer." (PMID 34882895, 2022). "They then analyzed the collected data and conducted more experiments to find that if the expression of the Bub3 gene was specifically suppressed, the proliferation and migration of cancer cells were reduced." (PMID 34882895, 2022). "Combining the scores of cytoplasmic BUB3 and CCNB1 improved risk stratification when integrated with the Cancer of the Prostate Risk Assessment post-Surgical (CAPRA-S) score (difference in concordance index = 0.024, 95% CI 0.001–0.05)." (PMID 31801961, 2020). "Deregulation of genes involved in the mitotic checkpoint, such as BUB3, CCNB1, and PTTG1, can contribute to cancer development by increasing the risk of incorrect cell division, aneuploidy, and genomic instability." (PMID 31801961, 2020).
cancer (continued). "In contrast with the general mechanism, previous studies have revealed that the involvement of Bub3 in SAC can be regulated in a manner specific for cancer cells." (PMID 30553276, 2018). "Unexpectedly, mitotic arrest only led to a slight increase of DMAP1/Bub3 interaction in cancer cells, implying certain cancer-specific signaling participate in the regulation of Bub3/DMAP1 complex formation." (PMID 30553276, 2018). "For example the SDL interaction between PPP2R5D and TTK or PPP2R2D and BUB3 were identified across six different cancers." (PMID 27557495, 2016). "Recent studies in cancer cells have shown that BuGZ is a novel SAC component that is required for chromosome alignment via stabilizing Bub3." (PMID 27177335, 2016). "This suggests that monitoring the levels of TTK, BUB1B, and BUB3 could potentially be useful in predicting the severity of carcinomas and guiding treatment decisions." (PMID 38987356, 2024). "BUB3 expression level was higher in N0, N1, N2, and N3 cancers than that in normal tissues." (PMID 36787437, 2023). "Furthermore, the different expression levels of BUB3 in COAD based on individual cancer stages were assessed using the TCGA database." (PMID 35156516, 2022). "This article discusses recent research progress into Bub3 in malignant tumors." (PMID 34882895, 2022). "This article will discuss the research progress of Bub3 in malignant tumors." (PMID 34882895, 2022). "BUB3 protein levels are also elevated in a wide variety of human cancers compared to normal tissue." (PMID 35631670, 2022). "The role of Bub3 in common cancer has been the subject of debate over the past few years." (PMID 34882895, 2022). "Specific inhibition of Bub3 gene expression reduced proliferation and migration of cancer cells." (PMID 34882895, 2022). "We examined the expression of BUB3 in various human cancer types." (PMID 35631670, 2022). "In addition, a number of studies have reported deregulated expression of the BUB3 gene in human cancers; however, its role in carcinogenesis is still controversial." (PMID 35631670, 2022). "As with other SAC genes, epigenetic deregulation remains the most common alteration in the BUB3 gene, while mutations at the sequence levels are rather rare and confer no increased cancer risk." (PMID 35631670, 2022). "In addition, PKM2 regulates chromosome segregation and mitosis in cancer by interacting with the spindle checkpoint protein Bub3." (PMID 34847775, 2021). "Our findings reveal Bub3/DMAP1 complex is crucial for responsive gene expression following mitotic arrest and demonstrate the survival advantage of cancer cells under mitotic stress is addicted to the inhibitory effect of c-Src on Bub3/DMAP1-mediated apoptosis." (PMID 30553276, 2018). "In consistence to this, our data indicates DMAP1 pY246 facilitates transcription of antiapoptotic-gene BCL2L1 under mitotic arrest in cancer cells, which is linked to its negative effects on Bub3 pS211-mediated DNA methylation at BCL2L1promoter." (PMID 30553276, 2018). "An extensive search for mitotic-checkpoint defects in human cancers has uncovered very infrequent mutations of mitotic-checkpoint genes and more frequent altered expression of mitotic-checkpoints genes BUB1, BUBR1, BUB3, MAD1, MAD2 [reviewed in Ref." (PMID 24377086, 2013). "These kind of abnormality could be generated by alterations in checkpoint genes (Bub1, BubR1, Bub3, Mad2) such as the heterozygozity observed both in human cancer cells and patients with the rare recessive disorder mosaic variegated aneuploidy." (PMID 21483691, 2011).
cancer (continued). "Moreover, overexpression of Bub3 can serve as an independent prognostic indicator for cancer‐specific survival, and may have an effect on increased cellular proliferation." (PMID 34882895, 2022). "Genes related to cancer stem cells and tumorigenesis, such as KPNA2, ECT2, ERCC6L and TUBB4B, and the cell-cycle regulators DLGAP5, KIF2C and BUB3 were also significantly upregulated in the CSPG+ group, and clustered well within the same area." (PMID 38251863, 2024). "This article provides a brief overview of the involvement of Bub3 in relation to the SAC and cancer." (PMID 34882895, 2022). "BUB3 and other SAC genes are frequently overexpressed in cancer, and such overexpression is correlated with chromosomal instability." (PMID 35631670, 2022). "The expression of BUB3, CCNB1, and PTTG1 has been shown to correlate with tumor grade and prognosis in some cancers." (PMID 31801961, 2020). "Together, this indicates a potential impact of the BUB3/RAE1-complex on longevity and cancer resistance in both mole rat species." (PMID 29084988, 2017). "Fourteen genes that are essential to prevent EDR in cancer cells also are essential to prevent aneuploidy in mice [AURKA, BUB1B, BUB3, KIF11, MAD2L1, TPX2, TTK, SGOL1." (PMID 27144335, 2016). "In fact, cancer cells quite frequently misregulate the expression of one or more critical SAC protein including Mad2, Bub3, Bub1, and BubR1." (PMID 27869759, 2016). "We found BUB3 to be significantly overexpressed in cancers compared to normal tissue in 16 of the 18 cancer types analyzed." (PMID 35631670, 2022). "In agreement with the observations in cancer cells, we find that protein level of Bub3 is markedly reduced upon knockdown of Zfp207, rather than that of Bub1, BubR1 and Mad2." (PMID 27177335, 2016).